ARC (activity regulated cytoskeleton associated protein)
Diseases named in the same sentence as ARC in open-access papers (continued):
Sharing a sentence is not in itself a finding about the gene and the disease.
cancer (18 papers, 2007 to 2025). A tumor composed of atypical neoplastic, often pleomorphic cells that invade other tissues. "On the other hand, lower levels of ARC (activity-regulated cytoskeleton-associated protein) involved in cell migration and cytoskeleton organization may indicate decreased cancer cell invasion." (PMID 37834191, 2023). "Having demonstrated CK2 inhibitor can efficiently attenuate the phosphorylation of endogenous ARC and significantly increased the susceptibility of cancer cells to DOX in vitro, we further investigated CK2 inhibitor therapeutic potential in mouse xenograft model." (PMID 26172393, 2015). "Furthermore, the elevated levels of ARC, a gene coding for an activity-regulated cytoskeleton-associated protein involved in cell migration, could lead to cancer cell progression." (PMID 37834191, 2023). "Hence, ARC may inhibit inflammation by regulating the proteoglycans in cancer-associated signaling pathways." (PMID 33995019, 2021). "Clinically, ARC overexpression serves as a predictor of tumor invasion and metastasis in human cancers." (PMID 41334581, 2025). "IHC showed that ARC was expressed more strongly in cancer tissues than in normal tissues, and was predominantly expressed in the cancer epithelium rather than in the stroma." (PMID 34083586, 2021). "High ARC expression contributed to chemotherapy resistance in cancer cells by targetting the mitochondrial fission machinery." (PMID 30126848, 2018). "It was also demonstrated that ARC expression was downregulated in cancer cells following DOX treatment." (PMID 25766316, 2015). "Taken together, we report here that phosphorylation of ARC by CK2 contributes to chemotherapy resistance by inhibiting DOX induced apoptosis, whereas, CK2 inhibitor increase the sensitivity of cancer cells to DOX by inhibiting the phosphorylation of ARC." (PMID 26172393, 2015). "Collectively, our data indicate that inhibition endogenous ARC phosphorylation by CK2 inhibitor make cancer cells more sensitive to DOX." (PMID 26172393, 2015). "And the decrease of phosphorylated ARC level consequentially makes cancer cells sensitive to apoptosis." (PMID 26172393, 2015). "Our current study found that cancer resistance to chemotherapy has a close relationship with the phosphorylated ARC which locates to mitochondrion in cancer cells." (PMID 26172393, 2015). "Our previous work has proved that highly expressed ARC contributed to chemotherapy resistance in cancer cells by targeting the mitochondrial fission machinery." (PMID 26172393, 2015). "The cytolocalization and the functions of phosphorylated ARC in cancer cells need to be further clarified." (PMID 26172393, 2015). "In light of the key role of ARC in controlling DOX-induced apoptosis both in cardiomyocytes and cancer cells, it is necessary to find out the molecular approaches that can downregulate ARC expression in cancer cells but upregulated ARC in cardiomyocytes." (PMID 25766316, 2015). "So we suppose that CK2 translocate to nuclear will catalyze the phosphorylation of ARC less effectively as unphosphorylated ARC predominantly distributed in cytoplasm in cancer cells." (PMID 26172393, 2015). "Meanwhile, our results showed that the localization of ARC in mitochondrial was decreased in cancer cells treated with DOX." (PMID 26172393, 2015). "Our previous works have proved that highly expressed ARC contributed to chemotherapy resistance in cancer cells and our present study revealed that ARC was phosphorylated and localized to mitochondria in HeLa and SGC-7901 cells." (PMID 26172393, 2015). "Our results showed that phosphorylated ARC localized to mitochondria and played a major part in chemotherapy resistance in cancer cells." (PMID 26172393, 2015). "Like IAPs, ARC has been found to be overexpressed in a variety of cancer cells, including glioblastoma, melanoma, and lymphoma cells, and in cancers from pancreas, colon, breast, lung, cervix and prostate." (PMID 23912235, 2013).
cancer (continued). "Additionally, the CNV condition and expression level of ASF1A, CDKN2A, MAGOHB, NADK, SPOP, and ARC were remarkably correlated in most cancer types." (PMID 37497116, 2023). "Although we have not investigated the extracellular function of ARC in the cancer microenvironment, it might be an attractive hypothesis that ARC mRNA can be transferred to neighboring cancer cells, where it also functions as an EMT inducer." (PMID 34083586, 2021). "This could dramatically elevate the importance of ARC channels from relative obscurity to a critical role in cancer progression." (PMID 32825277, 2020). "It is thus tempting to speculate that plasma membrane STIM1 and ARC channels may be important in cancer migration by sensing the tumour microenvironment." (PMID 32825277, 2020). "There are arguments about the subcellular localization of ARC in cancer cells." (PMID 26172393, 2015). "It is reported that ARC is highly expressed in many malignant tumors." (PMID 26172393, 2015). "In summary, our data indicate that CK2 inhibitor combined with low-dose DOX could synergistically down-regulate the phosphorylation of ARC and then induce cancer cells sensitive to undergoing apoptosis in vivo." (PMID 26172393, 2015). "Firstly, we detected whether ARC is phosphorylated and whether it locates to mitochondrion to perform its function in cancer cell lines." (PMID 26172393, 2015). "As CK2 is able to phosphorylate ARC, we wondered whether ARC regulated DOX sensitivity in cancer cells to undergoing apoptosis depending on CK2." (PMID 26172393, 2015). "Meanwhile it's unknown whether ARC is phosphorylated in cancer cells and whether T149 phosphorylation is essential for cancer resistance to chemotherapy." (PMID 26172393, 2015). "It's reported that ARC is predominantly distributed in the nuclei of some human cancer cell lines." (PMID 26172393, 2015). "We also observed that ARC expression was down-regulated in cancer cells following DOX treatment." (PMID 26172393, 2015). "While mitochondrial fission is related to the initiation of apoptosis and phosphorylated ARC locates to mitochondrion, enforced expression of ARC T149A could not inhibit mitochondrial fission as effectively as wtARC in cancer cells." (PMID 26172393, 2015). "Our further study showed that casein kinase II (CK2) inhibitors could decrease the phosphorylation levels of ARC and make cancer cells sensitive to undergoing apoptosis." (PMID 26172393, 2015). "The present study was designed to elucidate whether phosphorylated ARC was contributed to chemotherapy resistance in cancer and investigate the potential molecular mechanism." (PMID 26172393, 2015). "In addition, we also identified 6 upregulated genes not typically associated with cancer (ARC, C1orf167, CNGA3, KRT75, SPRR1B, STUM)." (PMID 38038766, 2024). "In addition, ARC was especially highly expressed in the invasive front of cancer." (PMID 34083586, 2021). "Interestingly, elevated ARC expression was also noted in human cancer cells." (PMID 26413214, 2015). "Thus, we attempted to figure out whether the decrease of phosphorylated ARC related to CK2 expression level or activity change in cancer cells treated with DOX." (PMID 26172393, 2015). "To better understand the phosphorylation is required for ARC to exert its anti-apoptotic function and exploring the potential mechanism by which ARC be phosphorylated, we detected whether inhibit endogenous ARC phosphorylation can control cancer cell apoptosis." (PMID 26172393, 2015). "However, the cytolocalization and the functions of phosphorylated ARC in cancer cells remain largely unknown." (PMID 26172393, 2015). "If we assume that PKC is a molecular target for ARC activity then this may explain the selective ability of ARC to kill cancer cells, since other PKC inhibitors have also been shown to have greater activity against cancer cells than their 'normal' counterparts." (PMID 19232100, 2009).
cancer (continued). "Our results identify a novel molecular mechanism for chemotherapy resistance involving phosphorylation of ARC by CK2 and provide a valuable insight into cancer therapy." (PMID 26172393, 2015). "Taken together, these results indicate that ARC requires to be phosphorylated at T149 to inhibit DOX induced apoptosis and maintain the mitochondrial morphology in cancer cells." (PMID 26172393, 2015). "As CK2 can phosphorylate ARC in cardiomyocytes to prevent apoptosis, it is necessary to investigate whether CK2 can target ARC in cancer cells to boost the tumorigenesis and induce the chemotherapy resistance." (PMID 26172393, 2015). "To study the role of phosphorylated ARC in DOX resistance, we treated cancer cells with DOX." (PMID 26172393, 2015). "ARC (NSC 188491, SMA-491), 4-amino-6-hydrazino-7-β-d-ribofuranosyl-7H-pyrrolo-(2,3-d)-pyrimidine-5-carboxamide, is a nucleoside analog with profound in vitro anti-cancer activity." (PMID 19232100, 2009). "Phosphorylated ARC could be detectable in cancer cells including HeLa and SGC-7901 but not in the normal HEK-293 cells." (PMID 26172393, 2015). "Taken together, our results revealed that CK2-mediated phosphorylation of ARC contributed to chemotherapy resistance by inhibiting DOX induced apoptosis and combining DOX with CK2 inhibitor could induce apoptosis of cancer cells synergistically by down-regulating the phosphorylation of ARC." (PMID 26172393, 2015). "Furthermore, we identified CK2α and CK2α' translates to nuclear in cancer cells under DOX treatment and this may go a step further to lower the ARC phosphorylation level by reducing the CK2 amount in cytoplasm." (PMID 26172393, 2015).
tumor (9 papers, 2007 to 2025). "In this work, SDT-induced ARC downregulation not only suppressed HCC tumor growth but may also attenuate metastasis and reverse chemoresistance." (PMID 41334581, 2025). "Moreover, Ras is capable to increase ARC on mRNA and protein levels in normal mamillary epithelium, hyperplastic regions of the mamillary epithelium and in derived tumours, while knockdown of Ras was shown to decrease both levels in breast cancer." (PMID 33579312, 2021). "However, ARC is also expressed in many different types of tumor, such as breast, lung, prostate, ovary, cervix, kidney, and colon, where it inhibits apoptosis in particular." (PMID 33579312, 2021). "The authors speculated that the increase in Orai3 expression and/or change in the tumour microenvironment (arachidonic acid) led to the recruitment of Orai1 subunits into the assembly of heteropentameric Orai1/Orai3 ARC channels." (PMID 32825277, 2020). "To validate these findings, we performed Western blotting analysis on tumor tissues from Group A and Group D. Consistent with sequencing data, HRK protein levels were elevated in Group D relative to Group A, while ARC expression was significantly reduced." (PMID 41334581, 2025). "Importantly, we did not detect the control anti-CD79b ARC in or near the tumor, indicating that the localization of the anti-TENB2 ARC components depended on the proper antibody–antigen interaction." (PMID 25550431, 2015).
psychiatric diseases (4 papers, 2017 to 2022). "Thus, it would be worthwhile investigating whether ARC also regulates ECM molecules in other psychiatric diseases." (PMID 35562887, 2022).
infection (3 papers, 2021 to 2025). The state of being infected such as from the introduction of a foreign agent such as serum, vaccine, antigenic substance or organism. "By combining transcriptome analysis and machine learning, we identified four key targets related to VVTT infection in A293 cells: ARC, JUNB, EGR3, and FOS." (PMID 39940969, 2025). "We have previously linked mRNA expression of both CAMK2B and ARC to synaptic function in our cell model and, interestingly, here both HSV-1 and HSV-2 decreased CAMK2B and ARC mRNA expression in cortical neurons 48 h post-infection." (PMID 34696502, 2021). "Additionally, we identified three critical targets during VVTT infection—ARC, JUNB, and EGR2—and further validated these targets using qPCR." (PMID 39940969, 2025).
adenocarcinoma (1 paper, 2022). A common cancer characterized by the presence of malignant glandular cells. "Since then, we believe that ARC may play a role in the development of adenocarcinoma to NEPC." (PMID 37255653, 2022).
neurological diseases (1 paper, 2022). "The second was the ARC gene, a neuronal gene that is essential for durable information storage in the mammalian brain and that has been implicated in various neurological diseases." (PMID 36155652, 2022).
ARC also shares sentences with these, for which no sentence is quoted: heart failure (6 papers); Tinnitus (3); autism (2); colon cancer (2); leukemia (2); mental disorder (2); acute myeloid leukemia (1); adenomyosis (1); Anxiety (1); asthma (1); brain diseases (1); cardiomyopathy (1); cognitive disorder (1); colorectal cancer (1); deafness (1); delirium (1); endometriosis (1); Huntington disease (1); Hyperammonemia (1); Hyperglycemia (1); lung carcinoma (1); lymphoma (1); memory impairment (1); Obesity (1); osteosarcoma (1); prion disease (1).